KCNC3 (potassium voltage-gated channel subfamily C member 3)
Description:
Voltage-gated potassium channel that plays an important role in the rapid repolarization of fast-firing brain neurons. The channel opens in response to the voltage difference across the membrane, forming a potassium-selective channel through which potassium ions pass in accordance with their electrochemical gradient. The channel displays rapid activation and inactivation kinetics. It plays a role in the regulation of the frequency, shape and duration of action potentials in Purkinje cells. Required for normal survival of cerebellar neurons, probably via its role in regulating the duration and frequency of action potentials that in turn regulate the activity of voltage-gated Ca(2+) channels and cellular Ca(2+) homeostasis (By similarity). Required for normal motor function. Plays a role in the reorganization of the cortical actin cytoskeleton and the formation of actin veil structures in neuronal growth cones via its interaction with HAX1 and the Arp2/3 complex.
Synonyms: Kv3.3; KSHIIID; SCA13
Tractability: Small molecule: an approved drug acts on it; it belongs to a druggable protein family. Antibody: UniProt places it where antibodies can reach, with high confidence; its Gene Ontology location is reachable by antibodies, with high confidence; UniProt predicts a signal peptide or a membrane-spanning region.
Gene: Protein-coding gene on chromosome 19 (50,311,937 to 50,333,515, reverse strand). Ensembl gene ENSG00000131398.
Subcellular location: Cell membrane; Presynaptic cell membrane; Perikaryon; Cell projection, axon; Cell projection, dendrite; Cell projection, dendritic spine membrane; Cytoplasm, cell cortex; Cytoplasm, cytoskeleton
Pathways (Reactome):
Neuronal System: Voltage gated Potassium channels
Gene Ontology:
Molecular function: protein binding; voltage-gated potassium channel activity; delayed rectifier potassium channel activity; gated channel activity; monoatomic ion channel activity
Biological process: cortical actin cytoskeleton organization; potassium ion transmembrane transport; potassium ion transport; protein tetramerization; action potential; monoatomic ion transport; protein homooligomerization; transmembrane transport
Cellular component: cell cortex; dendrite; plasma membrane; voltage-gated potassium channel complex; axon terminus; dendrite membrane; neuronal cell body membrane; postsynaptic membrane; presynaptic membrane; axon; cytoskeleton; dendritic spine membrane; membrane; perikaryon
Genetic constraint (gnomAD): Loss-of-function variants: 13 observed, 31.61 expected, observed/expected ratio (o/e) 0.41, 90% interval 0.27 to 0.65. The upper end of that interval is the gene's LOEUF score, 0.65, which puts it in group 2 of 6, group 1 being the genes least tolerant of losing a copy. Missense variants: 623 observed, 868.59 expected, observed/expected ratio (o/e) 0.72, 90% interval 0.67 to 0.77. Synonymous variants: 399 observed, 378.22 expected, observed/expected ratio (o/e) 1.05, 90% interval 0.97 to 1.15.
Gene-disease validity (ClinGen):
ClinGen rates the evidence that KCNC3 causes each of these diseases.
spinocerebellar ataxia type 13 (autosomal dominant): Definitive. Spinocerebellar ataxia type 13 (SCA13) is a very rare subtype of type I autosomal dominant cerebellar ataxia (ADCA type I).
Homologues: Orthologues: macaque KCNC3 (99% identical), dog KCNC3 (95% identical), pig KCNC3 (95% identical), chimpanzee KCNC3 (94% identical), guinea pig KCNC3 (93% identical), rat Kcnc3 (92% identical), mouse Kcnc3 (92% identical). Paralogues in human: KCNC1 (57% identical), KCNC4 (55% identical), KCNC2 (51% identical), KCNB2 (26% identical), KCNA4 (24% identical), KCNA3 (24% identical), KCNA1 (24% identical), KCNA2 (24% identical), KCNA5 (24% identical), KCNA6 (24% identical), KCND1 (23% identical), and 19 more.
Diseases named in the same sentence as KCNC3 in open-access papers:
KCNC3 is named in the same sentence as 44 diseases in open-access papers, as found by Europe PMC text mining. Sharing a sentence is not in itself a finding about the gene and the disease. The quoted sentences say what the papers report.
Ataxia (32 papers, 2011 to 2025). Ataxia refers to impaired coordination of voluntary muscle movement. "In humans, mutations in KCNC3 have been associated with spinocerebellar ataxia as well as hearing loss (69, –71), including an early-onset form of spinocerebellar ataxia with severe intellectual disability." (PMID 35881790, 2022). "Mutation associated with SCA type 13 alter KCNC3 function and expression in expression systems of Xenopus laevis which were injected by Filipino-cerebellar ataxia cDNA clone." (PMID 31263403, 2019). "SCA13 is an infrequent autosomal dominant cerebellar ataxia caused by point mutations in KCNC3, which encodes the Kv3.3 voltage-gated potassium channel, and its symptoms include intellectual disability, seizure and ataxia." (PMID 30283301, 2018). "Our objective was to describe the frequency of mutations associated with KCNC3 in a large cohort of index patients with sporadic or familial ataxia presenting to three US ataxia clinics at academic medical centers." (PMID 21479265, 2011). "Our present data support the notion that SCA13 is a rare ataxia and that KCNC3 mutations causing SCA13 have arisen in a number of ethnic groups." (PMID 21479265, 2011). "Interestingly, some cases corresponded to channelopathies associated with cognitive and motor delay, in which ataxia has also been described, including KCNC3, ITPR1, ATP1A3 and CTNNB1." (PMID 39048885, 2024). "In this study, we screened a total of 848 Dutch cerebellar ataxia patients for mutations in KCNC3, in order to identify novel SCA13 pathogenic mutations, to gain insights into their mode of pathogenesis, and to establish a crude estimate of SCA13 disease prevalence in the Dutch ataxia population." (PMID 25756792, 2015). "Mutations in KCNC3 are a rare cause of spinocerebellar ataxia with a frequency of less than 1%." (PMID 21479265, 2011). "Since interactions between the gene products of several ataxia loci, including β-III spectrin and Kv3.3, are currently being investigated, the KCNC3 variant c.-6C>A was further analyzed." (PMID 39596509, 2024). "The Kv3 subfamily is closely associated with neurological disorders, such as KCNC 3 (Kv3.3) missense mutations found in spinocerebellar ataxia and the absence of KCNC2 chromosomes in patients with neurodevelopmental retardation and ataxia." (PMID 35299674, 2022). "This paradox has already been described in other patients with ataxia and mutations in KIF1A, ITPR1, and PMPCA but also in KCNC3, and CACNA1A genes." (PMID 36233161, 2022). "We report findings from DNA sequence analysis of the human KCNC3 gene in a large mixed ethnicity American cohort of autosomal dominant early and late onset ataxia patients." (PMID 21479265, 2011). "DNA sequence analysis of the coding region of the KCNC3 gene was performed in 327 index cases with ataxia." (PMID 21479265, 2011).
spinocerebellar ataxia type 13 (23 papers, 2010 to 2025). "Pathogenic variants in KCNC3, which encodes the voltage-gated potassium channel Kv3.3, are associated with spinocerebellar ataxia type 13." (PMID 39596509, 2024). "Mutations in the KCNC3 gene cause cerebellar neurodegeneration and impair auditory processing, termed spinocerebellar ataxia type 13 (SCA13)." (PMID 35906672, 2022). "Consistent with these notions, both loss- and gain-of-function variants in the KCNC3 gene encoding another voltage-gated K+ channel (KV3.3) have been associated with spinocerebellar ataxia type 13." (PMID 34361012, 2021). "Mutations in KCNC3, the gene that encodes Kv3.3, result in spinocerebellar ataxia type 13 (SCA13), a human autosomal dominant disease, characterized by degeneration of the cerebellum and deficits in the processing of auditory information." (PMID 33741962, 2021). "Spinocerebellar ataxia type 13 (SCA13) is an autosomal dominantly inherited disorder caused by mutations in KCNC3 coding for the Kv3.3 voltage-gated potassium channel." (PMID 23912307, 2013). "Mutations in the coding DNA for Kv3.3 (KCNC3) result in a unique neurodegenerative disease termed spinocerebellar ataxia type 13 (SCA13) in mammals (including humans), a disease that can be genetically modeled in zebrafish." (PMID 37490159, 2023). "Interestingly, spinocerebellar ataxia type 13 (SCA13) caused by mutations in KCNC3/KV3.3, also exists in distinct forms which have been associated with a phenotypic spectrum that includes both non-progressive congenital-onset ataxia and (slowly) progressive infancy to adult-onset cerebellar ataxia." (PMID 34067185, 2021). "Mutations in KCNC3 have previously been reported to underlie autosomal dominant spinocerebellar ataxia type 13 (SCA13), although some variants of uncertain pathogenic significance have also been reported." (PMID 25981959, 2015). "Recently, KCNC3, which encodes Kv3.3, was identified as the gene mutated in spinocerebellar ataxia type 13 (SCA13)." (PMID 20712895, 2010). "Spinocerebellar ataxia type 13 (SCA13) is caused by missense mutations in the KCNC3 gene, which encodes the voltage-gated potassium channel Kv3.3." (PMID 33671313, 2021). "One of these genes is the KCNC3 gene, which is responsible for causing a distinctive form of SCA known as spinocerebellar ataxia type 13 (SCA13)." (PMID 37365508, 2023).
autosomal dominant cerebellar ataxia (4 papers, 2010 to 2019). A clinically and genetically heterogeneous group of neurodegenerative diseases characterized by a slowly progressive ataxia of gait, stance and limbs, dysarthria and/or oculomotor disorder, due to cerebellar degeneration in the absence of coexisting diseases. "Gain-of function or dominant-negative mutations in the voltage-gated potassium channel KCNC3 (Kv3.3) were recently identified as a cause of autosomal dominant spinocerebellar ataxia." (PMID 21479265, 2011).
atherosclerosis (2 papers, 2021 to 2022). A disease characterized by the build-up of fatty material and calcium deposition in the arterial wall resulting in partial or complete occlusion of the arterial lumen. "All these results suggested that knockdown of lnc-KCNC3-3:1 alleviates development of atherosclerosis via downregulation of JAK1/STAT3 signaling pathway." (PMID 34540913, 2021). "Taken together, knockdown of lnc-KCNC3-3:1 alleviates the development of atherosclerosis via downregulation of JAK1/STAT3 signaling pathway." (PMID 34540913, 2021). "Collectively, our data indicated that lnc-KCNC3-3:1 silencing inhibited the progression of atherosclerosis via inactivation of PI3K/Akt and JAK1/STAT3 signaling pathways." (PMID 34540913, 2021). "Consistent to in vitro data, the expressions of p-Akt, p-JAK1 and p-STAT3 in tissues of mice were notably increased in atherosclerosis group; however, these phenomena were completely reversed by lnc-KCNC3-3:1 siRNA1." (PMID 34540913, 2021). "Collectively, knockdown of lnc-KCNC3-3:1 alleviates the symptom of atherosclerosis via downregulation of JAK1/STAT3 pathway." (PMID 34540913, 2021). "The data indicated that the levels of TG and LDL-C were increased, and the level of HDL-C was decreased in atherosclerosis group; however, these changes were markedly reversed by lnc-KCNC3-3:1 siRNA1." (PMID 34540913, 2021). "In atherosclerosis model group, there was a significant increase in lipid accumulation and vascular wall thickening; however, these symptoms were notably alleviated by lnc-KCNC3-3:1 knockdown." (PMID 34540913, 2021). "Thus, we next focused on exploring the role of lnc-KCNC3-3:1 in the progression of atherosclerosis." (PMID 34540913, 2021). "In order to explore the function of LOC100129516, lnc-KCNC3-3:1, and ENSG00000261482.1 in the progression of atherosclerosis, specific siRNAs were used." (PMID 34540913, 2021). "Among these five lncRNAs, the increases of LOC100129516, lnc-KCNC3-3:1, and ENSG00000261482.1 were much higher in the in vitro model of atherosclerosis compared with the other two lncRNAs; thus, we focused on these 3 lncRNAs in the following experiments." (PMID 34540913, 2021). "Highly upregulated lncRNAs including LOC100129516, lnc-KCNC3-3:1 and ENSG00000261482.1 that were closely related to the occurrence and development of atherosclerosis were screened out." (PMID 34540913, 2021). "Animal study revealed that knockdown of lnc-KCNC3-3:1 alleviated the symptom of atherosclerosis, and it could inhibit the expressions of p-JAK1, p-STAT3 and p-Akt in tissues of atherosclerosis mice." (PMID 34540913, 2021).
Anxiety (1 paper, 2018). Intense feelings of nervousness, tension, or panic often arise in response to interpersonal stresses. "It remains to be determined how increased expression of Kcnc3 and Dagla in the Adar3exon3 mice modulates synaptic signaling and whether it contributes to the fear conditioning deficit and increased anxiety phenotype in these mice." (PMID 29719497, 2018).
bipolar disorder (1 paper, 2025). A disorder of the brain that causes unusual shifts in mood, energy, activity levels and the ability to carry out day-to-day tasks. "For instance, the influence of KCNC3 on both bipolar disorder and schizophrenia may manifest through epigenetic mechanisms." (PMID 39905509, 2025).
cerebral palsy (1 paper, 2015). A group of disorders affecting the development of movement and posture, often accompanied by disturbances of sensation, perception, cognition, and behavior. "However, two other mutations in KCNC3, R423H and P448L do cause a very rare non-progressive early onset autosomal dominant ataxia that is sometimes associated with mild mental retardation and normal imaging, reminiscent of our case and also of the phenotype of ‘cerebral palsy’." (PMID 25981959, 2015).
Onset (1 paper, 2020). The age group in which disease manifestations appear. "KCNC3 variants from infant-onset disease change channel gating properties and increase neuron excitability compared to variants from adult-onset disease, which were associated with reduced channel activity and high-frequency neuronal firing." (PMID 33551980, 2020).
progressive cognitive decline (1 paper, 2024). "In a patient with an ataxic movement disorder and progressive cognitive decline, the c.-6C>A variant was detected in the Kozak sequence of KCNC3." (PMID 39596509, 2024).
pulmonary edema (1 paper, 2024). Accumulation of fluid in the lung tissues causing disturbance of the gas exchange that may lead to respiratory failure. "KCNC3, KCNQ3, and KCNMA1 are voltage-gated potassium ion channel proteins, and the downregulation of KCNC3 and KCNQ3 in yak lungs suggested that the expression of voltage-gated potassium ion channels decreases in yaks with age, reducing membrane depolarization and harmful effects of pulmonary edema." (PMID 38779034, 2024).
Vertigo (1 paper, 2024). An abnormal sensation of spinning while the body is actually stationary. "Nevertheless, our study clearly associated non-dominant negative loss-of-function variants in KCNC3 with atypical SCA13, in which other phenotypes such as vertigo may dominate the clinical features." (PMID 39416683, 2024).
movement disorder (1 paper, 2024). Neurological conditions resulting in abnormal voluntary or involuntary movement, which may impact the speed, fluency, quality and ease of movement. "In a patient with an ataxic movement disorder, two variants of uncertain significance in the genes SPTBN2 and KCNC3 associated with SCA were detected." (PMID 39596509, 2024).
KCNC3 also shares sentences with these, for which no sentence is quoted: epilepsy (5 papers); cerebellar ataxia (4); cerebellar degeneration (3); channelopathies (3); neurodegenerative disease (3); neurological disorders (3); tumor (3); episodic ataxia type 1 (2); fragile X syndrome (2); progressive myoclonus epilepsy (2); Tremor (2); acquired ataxia (1); ataxic cerebral palsy (1); autosomal dominant disease (1); Boucher–Neuhauser Syndrome (1); cancer (1); cardiac hypertrophy (1); cognitive delay (1); colon cancer (1); deafness (1); dementia (1); electrolyte imbalance (1); hearing loss (1); hypertrophic cardiomyopathy (1); Intellectual disability (1); long QT syndrome type 1 (1); myoclonic epilepsy (1); Orofacial dyskinesia (1); psychosis (1); schizophrenia (1).
A further 2 diseases each share a sentence with KCNC3 in 1 paper.